CXCL2 (C-X-C motif chemokine ligand 2)
Diseases named in the same sentence as CXCL2 in open-access papers (continued):
Sharing a sentence is not in itself a finding about the gene and the disease.
melanoma (continued). "Studies using melanoma tumour models support the role of CXCL1, CXCL2, and CXCL3 in mediating tumour angiogenesis and levels of all three chemokines are highly expressed in melanoma tumours." (PMID 21298036, 2011). "However, CXCL1, CXCL2, CXCL3, CXCL5 and CXCL8 mRNAs were significantly upregulated in melanoma samples compared to benign nevi." (PMID 37270599, 2023). "Notably, gene expression sequences from melanoma biopsies also revealed a positive correlation between CCL5, CXCL2, CXCL9, and CXCL10 and clinical benefit in a phase II trial of a MAGE-A3 vaccine." (PMID 30899263, 2019). "Amelanotic C-32 melanoma cells produced less CXCL1, CXCL2, and CXCL8 than primary melanocytes." (PMID 30870978, 2019). "CXCL2 gene therapy with the HVJ-E vector was more effective at suppressing melanoma in mice than HVJ-E alone or an HVJ-E-containing empty plasmid without CXCL2 cDNA." (PMID 27259252, 2016). "Furthermore, exposure of melanoma cells to HFD serum induced the pro-inflammatory NF-κB pathway and also enhanced the expression of CXCL1, CXCL2 and CXCL5." (PMID 27049717, 2016). "Also, the chemokines CXCL1, CXCL2 and CXCL3 have been shown to play a role in the growth of pancreatic cancer, melanoma, lung cancer, adenocarcinoma and gastric cancer." (PMID 24259307, 2013). "In studies using neuroblastoma and melanoma murine models, the absence of CD200/CD200R signaling (using CD200R- mice) caused TAMCs to upregulate CCL24 and CCL8 levels but downregulate the production of CXCL3, CXCL2, and CCL3." (PMID 38137547, 2023). "In addition, other experimental studies revealed that adipocytes co-cultured with melanoma cells induce the secretion of chemoattractant factors (CXCL1, CXCL2, and CXCL5) added to a local immune cell recruitment, especially of M2 macrophages, in the “tumour niche”." (PMID 35334544, 2022). "CXCL2 was not expressed in M14 melanoma cells (data not shown)." (PMID 20030852, 2009). "Thus, the production of CCL24 and CCL8, and the reduction of CXCL3, CXCL2, and CCL3 in TAMCs, explain why mice lacking intact CD200/CD200R signaling more potently rejected neuroblastoma and melanoma tumors relative to wild-type conditions." (PMID 38137547, 2023).
psoriasis (37 papers, 2014 to 2026). An autoimmune condition characterized by red, well-delineated plaques with silvery scales that are usually on the extensor surfaces and scalp. "Chemokines encoded by CCR7, CCL2, CCL19, CXCL8, CXCL1, and CXCL2 genes have been identified as potential biomarkers of psoriasis." (PMID 40906403, 2025). "They introduced Card14ΔE138K/A mutations in mice with psoriasis and found an up-regulation of pro-inflammatory cytokines, IL-23, IL-19, IL-22 and IL-17; chemokines Cxcl1, Ccl20, and Cxcl2; and antimicrobial peptides, Lcn2 and Defb4." (PMID 36012602, 2022). "CXCL1 and CXCL2 recruit neutrophils, causing a breach of epidermal hyperproliferation, intraepidermal neutrophilic microabscess, which are the typical features of psoriasis." (PMID 36389813, 2022). "We found that, upon IL-36 stimulation, IκBζ was actively recruited to the promoter regions of its target genes, including genes encoding for the chemokines Csf3, Cxcl1, and Cxcl2 and the psoriasis-associated antimicrobial proteins Defb4 and S100a9." (PMID 31622280, 2019). "Mechanistically, this psoriasis protection was mediated by IκBζ deficiency in keratinocytes abrogating the induction of specific proinflammatory target genes, including Cxcl5, Cxcl2, Csf2, and Csf3, in response to IL-17A or IL-36." (PMID 31622280, 2019). "WY14643 treatment significantly downregulated psoriasis‐associated inflammatory cytokines and chemokines (Il17a, Il1b, Cxcl1, Cxcl2, Cxcl3, Cxcl15, and Csf3) as well as the antimicrobial peptides S100a8 and S100a9 in IMQ‐induced skin lesions at the transcriptional level." (PMID 40878384, 2025). "In this respect, we speculate that myeloid autophagy could control neutrophilic inflammation in psoriasis through a mechanism involving CXCL2; however, the exact underlying mechanism including other cytokines and chemokines requires further study." (PMID 38704587, 2024). "We cannot rule out the contribution of other regulatory mechanisms besides IL-1β and CXCL2 to neutrophilia and psoriasis pathogenesis caused by myeloid autophagy deficiency as we assessed the expression of a selected set of cytokines and chemokines central to inflammatory diseases." (PMID 38704587, 2024). "In addition, mice deficient in MKP1 overproduce pro-inflammatory cytokines, and MKP1 knockout mice are highly susceptible to imiquimod-induced psoriasis, in which enhancement of p38 phosphorylation and increased Cxcl1 and Cxcl2 expression are also observed." (PMID 36825199, 2023). "Among others, important psoriasis-associated target genes of IκBζ include certain chemo- and cytokines (e.g., Cxcl1, Cxcl2, Cxcl5, Ccl3, and Il17c) as well as antimicrobial proteins, such as S100 calcium-binding proteins (e.g., S100a9), β-defensin-2 (Defb4), and lipocalin-2 (Lcn2)." (PMID 31622280, 2019). "Furthermore, IL-1R1 blockade was found to alleviate psoriatic skin inflammation, decrease Cxcl2 expression, and diminish neutrophilia, suggesting that IL-1β dysregulation due to autophagy deficiency plays an important role in psoriasis pathogenesis by driving neutrophilic inflammation." (PMID 38704587, 2024). "A study reported that epidermal keratinocytes can also produce CXCL2 and recruit neutrophils to skin lesions of patients with psoriasis and its animal models." (PMID 40185981, 2025). "Namely, the previously published studies investigated the molecular interaction of quercetin and psoriasis genes CXCL2 and CXCR4, as well as Src family tyrosine kinases (SFKs)." (PMID 40806422, 2025). "The differential expression analysis identified several upregulated differentially expressed genes, including OSM, CXCL8, TREM1, CXCL1, CSF3R, BCL2A1 and CXCL2, in relapsed psoriasis skin compared with baseline lesional skin." (PMID 40181552, 2025). "To confirm the results obtained by RNA‐seq, we performed qPCR to detect and quantify CXCL1, CXCL2, CXCL8, CSFR3, OSM and TREM1, in addition to the psoriasis‐associated genes IL‐17A and IL‐23." (PMID 40181552, 2025).
psoriasis (continued). "Our study highlighted CCR7, CCL2, CCL19, CXCL8, CXCL1, and CXCL2 as potential inflammatory biomarkers in psoriasis, illuminating their molecular mechanisms." (PMID 38829444, 2024). "The study highlights six chemokine genes (CCR7, CCL2, CCL19, CXCL8, CXCL1, and CXCL2) as potential biomarkers in psoriasis, which are significantly involved in immune and inflammatory responses." (PMID 38829444, 2024). "In conclusion, our study highlights six chemokine genes (CCR7, CCL2, CCL19, CXCL8, CXCL1, and CXCL2) as potential biomarkers in psoriasis, providing insights into the immune and inflammatory responses as pivotal instances in disease pathogenesis." (PMID 38829444, 2024). "Epidermal keratinocytes produce chemoattractants, including CXCL2, and recruit neutrophils to the skin lesions of patients with psoriasis and its animal models." (PMID 38312837, 2024). "Fibroblasts produced a number of chemokines (CCL13, CCL19, CCL2, CCL8, CXCL1, CXCL12, CXCL2, CXCL3) that linked to receptors expressed by myeloid cells and T cells, suggesting an important role for fibroblasts in recruiting immune cells in psoriasis." (PMID 37308489, 2023). "We had found L-THE regulated chemokine signaling pathway and IL-17A signaling pathway associated genes, such as CXCL2, CCL3 and CCL4 in skin tissues from mice with psoriasis." (PMID 34381369, 2021). "Previous studies revealed an important contribution of keratinocyte-derived CXCL1 and CXCL2 to the development of psoriasis, as these chemokines trigger the infiltration of neutrophils into the skin." (PMID 31622280, 2019). "IL-8, CXCL1, and CXCL2 have been reported upregulated in the lesional skin of patients with AD or psoriasis." (PMID 24586752, 2014). "Therefore, it is likely that the CXCL2–IL-23–IL-17 loop in the EIME drives type 17 inflammation in patients with psoriasis." (PMID 38312837, 2024). "Our research revealed that elevated levels of CXCL1, CXCL2, and CXCL8 in psoriasis patients are significantly associated with the infiltration of immune cells such as T cells, neutrophils, and DCs, hence providing considerable diagnostic value with an AUC of 0.989, 0.963, and 0.982, respectively." (PMID 38829444, 2024). "In addition, real-time RT-PCR analysis showed that IL-1β, IL-17A, IL-36γ, CXCL1, and CXCL2 expression was increased in IMQ-induced psoriasis-like lesions in Il36rn−/− mice." (PMID 33214582, 2020). "Normal human keratinocytes were found to constitutively bear the IL-17 receptor (IL-17R) and they are able to produce several IL-17-induced inflammatory and immune-related mediators implicated in psoriasis pathogenesis (e.g. IL-8, CCL20, S100A12, CXCL1, and CXCL2)." (PMID 24587313, 2014). "Notably, differential expression analysis identified 1,530 up-regulated and 1,435 down-regulated genes in the PLEVP group compared to the model, with several psoriasis-related inflammatory markers (Il17a, Ccl2, Cxcl2, and Tnf) being significantly down-regulated." (PMID 40248109, 2025). "Furthermore, whereas psoriasis-related genes, such as Cxcl2, Cxcl1, and Il1f6, were significantly induced in the skin of K14-IL17Aind Ctrl mice, the same genes were expressed neither in skin samples nor in keratinocytes isolated from mice harboring an additional deletion of IκBζ in keratinocytes." (PMID 31622280, 2019). "Finally, the circulating immune cells infiltrate the skin and other organs, which might be further supported by IκBζ-dependent chemokines (e.g., Cxcl1, Cxcl2), and result in the establishment of full-blown psoriasis and systemic inflammation." (PMID 31622280, 2019). "SerpinB7 knockdown in HaCaT cells drastically increased the expression of psoriasis-related chemokines (CCL20, CCL27, CXCL1, CXCL2) and antimicrobial peptides LL37 and S100A8 in the M5-stimulated in vitro psoriatic model." (PMID 35864103, 2022).
psoriasis (continued). "According to our analysis, with the treatment of immunosuppressants in psoriasis, the expression of IL-37 increased gradually, while IL-19, CXCL1, CXCL2, CXCL13 decrease gradually." (PMID 36389813, 2022). "RT-PCR analysis showed that the mRNA levels of IL-23 P19, TNF-α, CXCL2 and S100A8 were significantly attenuated in back skin from IMQ-induced psoriasis mice." (PMID 34381369, 2021). "In accordance with the accumulation of neutrophils in psoriasis, the gene expression of neutrophilic cytochemokines CXCL1, CXCL2, CXCL8, and IL-36 is upregulated in the lesional skin of psoriasis." (PMID 32070069, 2020). "Similarly, in psoriasis, TOPK regulates neutrophil chemokines such as CXCL1, CXCL2, and CXCL8 by activating STAT3 and NF-κB p65 in keratinocytes, thereby promoting neutrophil infiltration and psoriasis progression." (PMID 41362722, 2026). "The transcriptional expressions of Cxcl1, Cxcl2, Il-1β, Il-1α, S100A8, S100A9, Il-6, and Vegf were significantly decreased in skin lesions of K14.Bsgfl/fl mice, indicating the proinflammatory role of the epidermal expression of CD147 in psoriasis." (PMID 37303600, 2023). "We determined the mRNA expression levels of several inflammatory cytokines that are important in psoriasis (TNF-α, IL-23p19, IL-17A, IL-22, IFN-α, IL-1β, IL-6, and IL-10) and a chemokine that promotes the migration of neutrophils (CXCL2) using quantitative real-time PCR." (PMID 32752186, 2020). "Furthermore, IL-1β stimulation of NHEKs was found to induce upregulation of the mRNA and protein levels of pro-inflammatory cytokines, chemokines and antibiotic peptides including IL-36γ, CXCL1, CXCL2, CCL20, S100A7, S100A8 and S100A9, which are closely related to the pathogenesis of psoriasis." (PMID 32194991, 2020). "In aggregate, these results suggest that neutrophils recruitment (a prominent feature of human psoriasis and many murine models of psoriasis) is, in part, regulated by TRPA1 through modulation of expression of neutrophil chemoattractants such as CXCL1 and CXCL2." (PMID 31111624, 2019). "The condition of keratinocytes for the transcription of these two genes, CXCL2 and HBEGF, in keratinocytes may contribute to the necessary and sufficient conditions for triggering inflammatory loops in the epithelial-immune microenvironment (EIME) in psoriasis." (PMID 38312837, 2024).
hepatocellular carcinoma (34 papers, 2014 to 2026). A malignant tumor that arises from hepatocytes. "Coincidentally, high expression levels of CXCR2 ligands, such as CXCL1, and CXCL2, have been found to be associated with the growth, invasion, and metastasis of hepatocellular carcinoma (HCC)." (PMID 36797756, 2023). "In hepatocellular carcinoma, overexpression of CXCL2 has been implicated in the inhibition of cell proliferation and concurrent promotion of apoptosis through upregulation of pro-apoptotic proteins such as Bax and Caspase-7." (PMID 33807638, 2021). "CCL26, for example, has been shown to be highly expressed in recurrent hepatocellular carcinoma (HCC), while CXCL2 is highly expressed in STK11-mutated NSCLC, which has a poorer response rate to ICIs." (PMID 35145511, 2021). "In the context of hepatocellular carcinoma, CXCL2 is downregulated in tumor tissues compared to adjacent normal tissues, and upregulation of CXCL2 inhibited angiogenesis and the aggressiveness of hepatocellular carcinoma." (PMID 35912252, 2022). "CXCL2 (C-X-C motif chemokine ligand 2) significantly enhanced the migration and invasion ability of hepatocellular carcinoma cells (HCCs)." (PMID 31781593, 2019). "The methylation status of CXCL2 was significantly different between normal and hepatocellular carcinoma tissues." (PMID 31781593, 2019). "miR-532-5p inhibits cell proliferation and metastasis by targeting the CXCL2 oncogene in hepatocellular carcinoma." (PMID 29324832, 2018). "However, several other studies reported down-regulated CXCL2 expression in hepatocellular carcinoma, possibly due to methylation-related mechanism." (PMID 34269159, 2021). "Monocytes-derived CXCL2 and CXCL8 are the main causes in regulating neutrophils' recruitment into TME of hepatocellular carcinoma, which could inhibit cancer cell apoptosis." (PMID 34474677, 2021). "Interestingly, CXCL2 was reported to be a direct target of hsa-miR-532-5p in hepatocellular carcinoma and this miRNA-gene interaction inhibited hepatocellular carcinoma cell proliferation and metastasis." (PMID 30662454, 2018). "Studies have shown that CXCL2 can enhance the proliferation and migration of SMMC7721 hepatoma cells." (PMID 38021148, 2023). "The CXCL2/CXCR2 axis also plays a role in immune evasion and resistance to therapy in different types of cancer, where SB225002 suppresses recruiting neutrophils and tumor growth under stress in hepatocellular carcinoma models." (PMID 41155662, 2025). "PFKFB3-NF-κB signaling induced the production of CXCL2 and CXCL8 in tumor-infiltrating monocytes, increased levels of CXCL2 and CXCL8 in monocytes and promote infiltration of oncostatin M-producing neutrophils in human hepatocellular carcinoma tissues." (PMID 37253634, 2023). "Similarly, in gastric, colorectal, and hepatocellular carcinoma serum CXCL1 and CXCL2 correlate with tumor size, metastasis, and decreased overall survival." (PMID 35332119, 2022). "CXCL2 could also activate the STAT3 signalling pathway, which then regulates PD-L1 expression, in hepatocellular carcinoma cell lines." (PMID 31462002, 2019). "For instance, M2 TAMs release paracrine factors, CXCL1 and CXCL2, which enhance resistance to sorafenib (SOR) in advanced-stage hepatocellular carcinoma (HCC) cells." (PMID 39919692, 2025). "Therefore, we speculated that FNDC4 might play an inhibitory role in hepatocellular carcinoma by affecting the expression activity of some inflammatory cytokines, such as CD40, TNFSF14 or CXCL2." (PMID 38021165, 2023). "However, in HEPG2 cells, a hepatocellular carcinoma cell line, CXCL2 promoter was activated 5-fold rather than inhibited by GR and DEX." (PMID 39619227, 2023). "In addition to that, five miRNAs (miR-124-3p, miR-34a-5p, miR-1-3p, miR-7-5p, and miR-99b-5p) were found in human cells that might target four hub genes (CXCL2, MMP9, SPP1, and SRC), which are related to inflammatory bowel disease (IBD) and hepatocellular carcinoma (HCC)." (PMID 37298833, 2023).